SLC35H1 (solute carrier family 35 member H1)
Description:
Putative GDP-fucose transporter.
Synonyms: C20orf5; OVCOV1; SLC35C2; CGI-15; bA394O2.1
Tractability: Antibody: UniProt predicts a signal peptide or a membrane-spanning region. PROTAC: ubiquitination databases record sites on it.
Gene: Protein-coding gene on chromosome 20 (46,345,980 to 46,364,458, reverse strand). Ensembl gene ENSG00000080189.
Subcellular location: Golgi apparatus, cis-Golgi network membrane; Endoplasmic reticulum-Golgi intermediate compartment membrane
Subcellular location (Human Protein Atlas): Golgi apparatus; Nucleoplasm
Gene Ontology:
Biological process: UDP-glucose transmembrane transport
Cellular component: cis-Golgi network; endoplasmic reticulum-Golgi intermediate compartment; endoplasmic reticulum-Golgi intermediate compartment membrane; Golgi apparatus
Genetic constraint (gnomAD): Loss-of-function variants: 27 observed, 38.38 expected, observed/expected ratio (o/e) 0.7, 90% interval 0.52 to 0.97. The upper end of that interval is the gene's LOEUF score, 0.97, which puts it in group 4 of 6, group 1 being the genes least tolerant of losing a copy. Missense variants: 404 observed, 483.9 expected, observed/expected ratio (o/e) 0.83, 90% interval 0.77 to 0.91. Synonymous variants: 225 observed, 214.55 expected, observed/expected ratio (o/e) 1.05, 90% interval 0.94 to 1.17.
Homologues: Orthologues: chimpanzee SLC35C2 (100% identical), macaque SLC35C2 (99% identical), dog SLC35C2 (97% identical), pig SLC35C2 (97% identical), mouse Slc35c2 (95% identical), rat Slc35c2 (95% identical), guinea pig SLC35C2 (94% identical), rabbit SLC35C2 (84% identical), zebrafish slc35c2 (65% identical), Drosophila melanogaster CG14971 (39% identical), Caenorhabditis elegans Y47G6A.7 (36% identical). Paralogues in human: SLC35E2B (21% identical), SLC35E3 (18% identical), SLC35C1 (17% identical), SLC35D2 (16% identical), SLC35E4 (16% identical), SLC35D3 (15% identical), SLC35D4 (14% identical), SLC35E1 (14% identical), SLC35D1 (13% identical).
Diseases named in the same sentence as SLC35H1 in open-access papers:
SLC35H1 is named in the same sentence as 4 diseases in open-access papers, as found by Europe PMC text mining. Sharing a sentence is not in itself a finding about the gene and the disease.
SLC35H1 shares sentences with these, for which no sentence is quoted: Alzheimer disease (1 paper); Anxiety (1); central nervous system diseases (1); viral infection (1).